FANCB (FA complementation group B)
Description:
DNA repair protein required for FANCD2 ubiquitination.
Synonyms: FAAP95; FAB; FLJ34064; FA2; FAAP90; FACB
Tractability: PROTAC: ubiquitination databases record sites on it.
Gene: Protein-coding gene on chromosome X (14,690,388 to 14,873,255, reverse strand). Ensembl gene ENSG00000181544.
Subcellular location: Nucleus
Pathways (Reactome):
DNA Repair: Fanconi Anemia Pathway
Immune System: PKR-mediated signaling
Gene Ontology:
Molecular function: protein binding
Biological process: interstrand cross-link repair; negative regulation of double-strand break repair via homologous recombination; positive regulation of double-strand break repair via homologous recombination; replication-born double-strand break repair via sister chromatid exchange
Cellular component: chromatin; Fanconi anaemia nuclear complex; cytosol; nucleoplasm; nucleus
Gene-disease validity (ClinGen):
ClinGen rates the evidence that FANCB causes each of these diseases.
Fanconi anemia complementation group B (X-linked): Definitive.
Homologues: Orthologues: chimpanzee FANCB (99% identical), macaque FANCB (96% identical), dog FANCB (72% identical), pig FANCB (72% identical), rabbit FANCB (70% identical), rat Fancb (50% identical), mouse Fancb (49% identical), tropical clawed frog fancb (34% identical), zebrafish fancb (20% identical).
Diseases named in the same sentence as FANCB in open-access papers:
FANCB is named in the same sentence as 45 diseases in open-access papers, as found by Europe PMC text mining. Sharing a sentence is not in itself a finding about the gene and the disease. The quoted sentences say what the papers report.
Fanconi anemia (22 papers, 2013 to 2025). Fanconi anemia (FA) is a hereditary DNA repair disorder characterized by progressive pancytopenia with bone marrow failure, variable congenital malformations and predisposition to develop hematological or solid tumors. "Fanconi anemia (FA) is a largely autosomal recessive inherited bone marrow failure syndrome, except for FA complementation group B (FANCB), which is X-linked recessive, and FANCR/RAD51, which exhibits autosomal dominant cellular effects." (PMID 40970532, 2025). "FANCB missense mutations were shown to cause the instability of the catalytic module and Fanconi Anemia (FA) core complex dysfunction." (PMID 39456660, 2024). "We next exposed human Nalm6 cells deficient in FANCB, another Fanconi Anaemia DNA crosslink repair gene, to FA in the presence of L-BSO." (PMID 35136057, 2022). "FANCB gene variants are X-linked recessive genes associated with Fanconi anemia." (PMID 38594752, 2024). "Dysregulation of genes related to NER (FANCB and FANCD2), BER (MBD4), and Fanconi anemia (FANCB and FANCD2) was also observed." (PMID 39728796, 2024). "The Fanconi anemia genes FANCB and FANCA exhibited recurrent amplifications and losses in 37 and 20% sarcoma cases, respectively." (PMID 36779660, 2023). "The Fanconi anemia pathway genes FANCB, POLN, DCLRE1A, UBA52, and FANCF genes were significantly (p < 0.01, T-test) downregulated after radiation only in FANCA-deficient HIO lines." (PMID 32085439, 2020). "Whole FANCB gene deletions in males with Fanconi anemia presenting as VACTERL have been reported twice, in both cases the aberrations were detected by array-CGH screening." (PMID 24416387, 2014). "FANCB is a part of the Fanconi anemia complementation group (FANC)." (PMID 38594752, 2024). "Other common genetic etiologies associated with EA/TEF include chromosomal disorders (trisomy 21, trisomy 18, trisomy 13), Feingold syndrome (MYCN), Fanconi anemia (multiple genes including FANCB, FANCC, FANCG, BRIP1) and other recurrent deletion and duplication syndromes." (PMID 36909054, 2023). "Common gene copy losses represented by both models with HNC patient relevance are Robo2, an important candidate tumor suppressor of the ROBO–SLIT pathway (16qC3), and Fancb gene (XqF5, human FANCB) involved in the Fanconi anemia (FA) pathway, which is altered in subsets of HNC patients." (PMID 33053752, 2020). "Additionally, we found 7 monoallelic pathogenic variants (2%, 7/327) in 6 genes (besides BRCA1/2) of the interstrand crosslink DNA repair Fanconi anemia pathway (FANCB, FANCC, FANCF, FANCI, FANCL, FANCM) and 1 in RAD51C, a Fanconi-like phenotype gene." (PMID 30262796, 2018). "Three members of the Fanconi Anemia pathway (FANCB, FANCC, and FANCL) were also down regulated." (PMID 24098381, 2013). "Additionally, Su-Dhl-4 cells treated with entinostat or tazemetostat also showed downregulation of RAD51, RAD54L, BRCA2, and three Fanconi anemia genes (FANCA, FANCB, and FANCM)." (PMID 31829282, 2019). "Furthermore, Nalm6 cells lacking FANCB were significantly sensitive to GSH inhibition even in the absence of FA, which might be a consequence of an increase in endogenous free FA, overall suggesting that GSH supply might be fundamental for Fanconi Anaemia patients." (PMID 35136057, 2022).
ovarian carcinoma (6 papers, 2020 to 2025). A malignant neoplasm originating from the surface ovarian epithelium. "The current study developed a predictive model of CSOARG for prognosis in ovarian cancer using eight key genes (WNK1, ANGPTL4, AREG, IGF1, CXCL10, GMPR, FANCB, LYG1)." (PMID 40510161, 2025). "The expression levels of six genes were found to be significantly elevated in ovarian cancer cells, except for FANCB and IGF1, which were not statistically significant." (PMID 40510161, 2025).
anemia (4 papers, 2010 to 2024). A reduction in the number of red blood cells, the amount of hemoglobin, and/or the volume of packed red blood cells. "For example, mutations in the Fanconi anemia group B (FANCB) gene are present in men with X-linked Fanconi anemia and are associated with infertility in male mice." (PMID 34270549, 2021). "FANCB, one of the Fanconi anemia proteins, is involved in the repair of DNA lesions and its upregulation is suggested to be required for the survival of colon cancer." (PMID 32703154, 2020). "FANCB, a member of Fanconi anemia complementation group (FANC) on chromosome X, was also confirmed to be inactivated on one allele in HCC1954." (PMID 21108794, 2010).
glioma (3 papers, 2021 to 2025). A benign or malignant brain and spinal cord tumor that arises from glial cells (astrocytes, oligodendrocytes, ependymal cells). "In our selection of seven HRD-related genes, the high expression of PLK3, PRMT6, UNG, and FANCB is associated with poorer prognosis in glioma patients, whereas the high expression of POLR2F, INO80D, and PTEN is linked to better prognosis." (PMID 41417782, 2025). "While all 4 target genes predicted reduced OS and PFI in LGG patients, both FANCB and TOP2A showed a protective role in the risk score model, indicating the controversial effect of FANCB and TOP2A in glioma patients." (PMID 34868977, 2021).
bone marrow failure (2 papers, 2015 to 2024). "A cohort study of 19 children with the deletion variant in FANCB demonstrated the earlier onset of bone marrow failure and more severe congenital abnormalities than those in the missense group." (PMID 38594752, 2024). "A previous study has also shown that individuals with FANCB variants have an earlier onset of bone marrow failure and more severe congenital anomalies than those without these variants." (PMID 38594752, 2024).
familial cancers (2 papers, 2020 to 2024). "A prospective cohort of 1021 unrelated cancer cases with clinical suspicion of hereditary cancer was screened for mutations in the following 14 FA genes: FANCA, FANCB, FANCC, FANCD2, FANCE, FANCF, FANCG/XRCC9, FANCI, FANCL/PHF9, FANCM, FANCP/SLX4, FANCQ/ERCC4, FANCR/RAD51 and FANCU/XRCC2." (PMID 32235514, 2020).
Hydrocephalus (2 papers, 2018 to 2024). Hydrocephalus is an active distension of the ventricular system of the brain resulting from inadequate passage of CSF from its point of production within the cerebral ventricles to its point of absorption into the systemic circulation. "Patients harboring X‐linked FANCB pathogenic variants usually present with severe congenital malformations resembling VACTERL syndrome with hydrocephalus." (PMID 29193904, 2018). "In our review, we found that the phenotypes of FANCB were microcephaly, hydrocephalus, tracheoesophageal fistula, external auditory canal stenosis, esophageal fistula, and microphthalmia." (PMID 38594752, 2024).
Allergy (1 paper, 2021). An allergy is an immune response or reaction to substances that are usually not harmful. "We found that SMC4 and FANCB are independent predictors for survival, and TOP2A, mold/dust allergy and preoperative corticosteroids are independent predictors for the PFI of LGG patients." (PMID 34868977, 2021).
Intellectual disability (1 paper, 2021). "His X-linked intellectual disability panel was notable for four potential disease-causing variants (in each of ATRX, FANCB, ZNF81, and ARX), but all were of undetermined significance." (PMID 34575122, 2021).
leukemia (1 paper, 2023). A malignant (clonal) hematologic disorder, involving hematopoietic stem cells and characterized by the presence of primitive or atypical myeloid or lymphoid cells in the bone marrow and the blood.
lung carcinoma (1 paper, 2022). "Compared with the carriers of AA genotype, the individuals with FANCB rs754552650 A/G genotype had a lower risk of lung cancer (OR=0.035, 95%CI: 0.020-0.062, P < 0.001)." (PMID 36172730, 2022). "In the Chinese population, the lung cancer risk of the individuals with FANCB rs754552650 A/G genotype was significantly decreased." (PMID 36172730, 2022). "This study intends to investigate the relationship between SNPs of CDH1, FANCB, APC genes and lung cancer genetic susceptibility." (PMID 36172730, 2022).
microtia (1 paper, 2024). "In the non-syndromic microtia group, the most frequently found gene was GSC exon 2 (25%; 6) and FANCB (16.67%); HOXA2, GSC exon 3, MARS1, CDT1 were found respectively in two (8.33%) cases." (PMID 38594752, 2024). "As reported in this review, the major gene disorder related to microtia phenotype is found in TCOF1 (32.82%; 28 cases), followed by GSC exon 2 (6.82%), FANCB (4.55%), SIX2 (3.41%), HSPA9 (3.41%) and CDT1 (3.41%) with each characteristic." (PMID 38594752, 2024). "We found 88 cases of genetic data related to microtia, including TCOF1 (31.82%), GSC exon 2 (6.82%), FANCB (4.55%), SIX2 (3.41%), HSPA9 (3.41%), and CDT1 (3.41%)." (PMID 38594752, 2024). "In the syndromic microtia group, the most common genes were TCOF1 (43.75%), SIX2 (4.69%), and HSPA9 (4.69%), while in the non-syndromic microtia group, the most frequently found gene was GSC exon 2 (25%), FANCB (16.67%), HOXA2 (8.33%), GSC exon 3 (8.33%), MARS1 (8.33%), and CDT1 (8.33%)." (PMID 38594752, 2024). "Based on our findings, 64 cases (72.72%) were syndromic microtia [TCOF1 (43.75%), SIX2 (4.69%), and HSPA9 (4.69%)] and 24 cases (27.27%) were non-syndromic microtia [GSC exon 2 (25%), FANCB (16.67%), HOXA2 (8.33%), GSC exon 3 (8.33%), MARS1 (8.33%), CDT1 (8.33%)]." (PMID 38594752, 2024).
ventricular septal defect (1 paper, 2018). The presence of a defect (opening) in the septum that separates the two ventricles of the heart. "A male infant (DECIPHER ID 256757) was reported with a 531 kb deletion that involved FANCB and had cardiac defects (ventricular septal defect), trachea‐esophageal fistula, renal hypoplasia, and skeletal abnormalities." (PMID 29490426, 2018).
cancer (10 papers, 2018 to 2025). A tumor composed of atypical neoplastic, often pleomorphic cells that invade other tissues. "Heterozygous variants in BLM and FANCB (in females) have the potential to be associated with increased susceptibility to cancer." (PMID 31937788, 2020). "FANCB is also reported to be associated with other types of cancers." (PMID 32703154, 2020). "Interestingly, the ZRSR2 gene locus is located close to BRCC3 and FANCB on the X chromosome and is homozygously deleted in 6.63% of all cancers through a LINE-1 element retrotransposition event occurring at Xp22.230,31." (PMID 41006228, 2025). "Interestingly, according to the current state of the knowledge, the FANCB role in cancer seems discrepant." (PMID 39456660, 2024). "Additionally, three unsolicited variants in ATR, BLM (in two individuals), and FANCB genes presented potential cancer susceptibility, were not reported to patients." (PMID 31937788, 2020). "The five genes (FANCB, KIF15, KIF4A, ERCC6L, and UBE2C) are all involved in fundamental cellular functions and found in many types of cancers." (PMID 32703154, 2020).
tumor (10 papers, 2020 to 2025). "As proven in the present study, the list of genes from the 44-gene panel more frequently mutated in BOT compared to the other tumor groups (FANCB, SEM1, FANCA, BRCA2, CHEK2, MUTYH, RAD50) was much longer than analogically altered genes in the hot-spot panel (KRAS only)." (PMID 39456660, 2024). "In vitro, downregulation of FANCB reduced tumor cell proliferation and attenuated invasive and migratory capacities." (PMID 41417782, 2025). "Quantitative PCR showed that FANCB expression was higher in the tumor core than in the peritumoral tissue." (PMID 41417782, 2025). "In the present study, we clarified that expression of FANCB, KIF15, KIF4A, ERCC6L, and UBE2C are regulated by DNA methylation changes of their promoter CpGis and closely associated with tumor prognosis in HCC using the TCGA database." (PMID 32703154, 2020). "Among the multiple phenotypes identified for the clinical presentation of FA, patients with FAAAP100, FANCB, or FANCL mutations may be best classified as having a high multiple congenital anomaly (MCA), low neoplasia phenotype due to impaired ICL repair rather than homologous recombination repair." (PMID 40232843, 2025).
hematological disease (1 paper, 2025). "The most severe phenotypes usually present in patients with whole-gene deletions of FANCB, whereas patients with point mutations in FANCB present with milder phenotypes such as later-onset hematological disease with no or fewer developmental abnormalities." (PMID 40244696, 2025).
FANCB also shares sentences with these, for which no sentence is quoted: breast carcinoma (4 papers); Infertility (2); Alpha-thalassemia (1); anal atresia (1); bone marrow failure syndrome (1); breast tumors (1); Bruton agammaglobulinemia (1); cardiovascular disease (1); chromosomal disorder (1); colon cancer (1); Diamond-Blackfan anemia (1); duodenal atresia (1); dyskeratosis congenita (1); endometrial cancer (1); external auditory canal stenosis (1); Feingold syndrome (1); hypogonadism (1); ischemic stroke (1); lymphoid neoplasm (1); microcephaly (1); microcytic anemia (1); microphthalmia (1); myeloid neoplasm (1); pancreatic cancer (1); pancreatic ductal adenocarcinoma (1); prostate carcinoma (1); sarcoma (1); skin cutaneous melanoma (1); Tracheoesophageal fistula (1).